MIR196A2 (microRNA 196a-2)
Synonyms: hsa-mir-196-2; hsa-mir-196a-2; MIRN196-2; MIRN196A2; mir-196a-2
Gene: MicroRNA gene on chromosome 12 (53,991,738 to 53,991,847, forward strand). Ensembl gene ENSG00000207924.
Gene Ontology:
Biological process: miRNA-mediated post-transcriptional gene silencing
Cellular component: RISC complex
Homologues: Orthologues: dog MIR196A2 (100% identical), macaque mml-mir-196a-2 (100% identical), chimpanzee ptr-mir-196a-2 (99% identical), rabbit MIR196A2 (98% identical), rat Mir196a (98% identical), pig ssc-mir-196a-2 (95% identical), guinea pig MIR196A2 (77% identical), mouse Mir196a-2 (77% identical), tropical clawed frog xtr-mir-196a (77% identical), zebrafish mir196a-1 (76% identical), zebrafish mir196c (75% identical). Paralogues in human: MIR196B (57% identical), MIR196A1 (49% identical).